STAT3 (signal transducer and activator of transcription 3)
Diseases named in the same sentence as STAT3 in open-access papers (continued):
Sharing a sentence is not in itself a finding about the gene and the disease.
cancer (continued). "STAT3 plays important role in tumorigenesis and in progression of cancer which allow STAT3 to arise as a promising molecule target in the treatment of cancer." (PMID 36557997, 2022). "Abnormal activation of the Jak/STAT3 signaling pathway increases the probability of stem cell transition and eventually induces cancer." (PMID 36620587, 2022). "Similar to gp130, vesicular Anx II coupling with STAT3 stimulates other signaling pathways in M2 polarization including the p38MAPK, and NF-κB pathways in macrophages, leading to augmented IL-6 and cancer progression." (PMID 36612080, 2022). "Studies conducted in cancer cells showed that direct interactions between STAT3 and NF-κB contribute to inflammation." (PMID 36050500, 2022). "In cancer cells, abnormal IL-6 expression and constitutive hyperactivation of STAT3 are closely correlated with an enhanced cancer cell proliferation and drug resistance." (PMID 35813468, 2022). "Next, we aimed to investigate the effect of SBT-100 on immune checkpoint inhibitors in cancer cells, such as PD-L1, a transcriptional gene target of STAT3." (PMID 35886918, 2022). "STAT3 activation as a transcriptional factor promotes a plethora of genes that contributes too many cancer hallmarks, thereby highlighting the tumorigenic role of STAT3 in HCC." (PMID 35401182, 2022). "While CD47 and STAT3 showed strong heterogeneity in late-stagecolorectal cancer, TAGL was highly expressed in the early- and late-stagecolorectal cancers." (PMID 35605973, 2022). "We observed that downregulation of the STAT3 target genes Bcl-xL and Cyclin D1 was correlated with mc-1Stat3 activity after treatment of 4T1 cancer cells in vitro and also of 4T1 cell-bearing mice." (PMID 35847174, 2022). "Signal transducer and activator of transcription 3 (STAT3) signaling is well known in cancer progression to promote glucose metabolism, leading to glycolysis by upregulating HK2." (PMID 35742904, 2022). "STAT3 has been shown to function in cell differentiation, antiapoptotic response, cancer metastasis, and regulating cancer hallmarks, such that it potentiates drug resistance and correlates with highly invasive OVCA cells." (PMID 36077501, 2022). "In many cancers, STAT3 is activated and plays a pivotal role in cellular proliferation, invasion, migration, and angiogenesis." (PMID 36000726, 2022). "IL-6/JAK2/STAT3 signaling pathway plays a crucial role in the development and progression of cancer." (PMID 36591515, 2022). "STAT3 and STAT2 belong to STAT family and are involved in STAT signaling, which are highly associated with TME and cancer progression." (PMID 35902970, 2022). "In the interest of novelty and therapeutic potential in cancer stroma, we focused the remainder of this study on the link among Pdia4, Stat3 and the Vegf proteins in cancer stroma." (PMID 35170261, 2022). "In the presence of IFN-γ, cancer cells can release several immunosuppressive mediators, including PD-L1 and transcriptional activator 3 (STAT3)." (PMID 35799780, 2022). "S1P is implicated as a pro-tumorigenic factor which activates signaling pathways including Ras/ERK, PI3K/RAC, STAT3, and PLC which are associated with various cancers." (PMID 36224630, 2022). "For example, LINC00115 and CASC9 can further regulate STAT3 function by regulating downstream miRNA in cancer disease." (PMID 36291659, 2022). "Other studies indicate that STAT3 (Signal Transducer and Activator of Transcription 3) and NF-κB (Nuclear factor-κB) signaling pathways play an important role in the maintenance of cancer stem-like properties in cancer cells." (PMID 35740529, 2022). "STAT3 is considered to have an important regulatory effect on the behavior of cancer stem-like cells." (PMID 35087591, 2022). "Hyperactive STAT3 drives cancer progression by promoting cell proliferation, angiogenesis, migration, invasion, and immune invasion." (PMID 36479072, 2022).
cancer (continued). "This highlights the JAK/STAT3 signaling cascade as an important therapeutic consideration in developing a multi-target cancer therapy." (PMID 36428556, 2022). "Naringenin has been well documented in managing the cancer cell growth and proliferation, migration, and multi-drug resistance both in in vitro and in vivo by targeting signaling pathways such as Jak/Stat3, Notch1, p38/MAPK, NF-ҡB, PI3K/Akt, and COX2." (PMID 35740529, 2022). "It is therefore difficult to determine if the anti-cancer effects observed when anti-PD-1 therapy was combined with STAT3-targeting curcumin was specific to STAT3-mediated effects or if other pathways were involved." (PMID 35053592, 2022). "The JAK2/STAT3 pathway is responsible for differentiation, cell growth, immune function, and activation, forming solid tumors in different cancers." (PMID 36500220, 2022). "Molecular mechanism studies have shown that MPSE or PGG can enhance HNSCC radiation sensitivity by targeting cancer stem cells via attenuated STAT3 activation to overcome resistance and improve clinical outcomes for patients." (PMID 35215350, 2022). "Of further note, previous studies have demonstrated the dysfunctional activation of STAT-3 in cancer and the significance of STAT-3 activation in abnormal cell proliferation and malignant transformation." (PMID 35740967, 2022). "Interestingly, it has been shown that IL-6 can be secreted both by cancer and stromal cells like cancer associated fibroblasts (CAFs), TAMs, and endothelial cells in various cancers and induces proliferation, angiogenesis and metastasis by activating STAT-3 pathway." (PMID 35300689, 2022). "STAT3 and its downstream effectors, such as Survivin and Bcl-2, regulate multiple processes that are critical for cancer development, involving tumorigenesis and growth, cell death, cellular senescence, metastasis, and differentiation." (PMID 36276282, 2022). "The degrader 114 (SD-91) represented a promising STAT3 degrader for the treatment of human cancers and other diseases related to STAT3 overactivation." (PMID 35680848, 2022). "IL-6 is a well-established inducer of STAT3 signaling, and STAT3 signaling mediates cancer proliferation." (PMID 35260569, 2022). "Activation of IL-6/JAK2/STAT3 pathway is closely associated with EMT and stem cell-like features, ultimately leading to poor outcomes in various human cancer patients." (PMID 36591515, 2022). "The use of agents acting on Nrf2, STAT3, Src, and NF-κB, etc., can be looked into in various cancers aggravated by oxidative stress, such as estrogen-dependent breast cancer and steatohepatitis." (PMID 36145523, 2022). "Induced STAT3 in cancer results in the upregulation of specific cytokines that in turn activate STAT3 in multiple immune cells such as Tregs." (PMID 36556226, 2022). "Similar inhibition of STAT3 signaling in some cancers, including HCC was reported when treating with sorafenib, bevacizumab, ramucirumab, panitumumab, and a combination of sorafenib with an anti-EGFRvIII53." (PMID 36284117, 2022). "The pathway analyses indicated significant alterations in several cancer-related signaling pathways, such as oxidative stress, STAT3, ERK/MAPK, interleukin and cytokine signaling pathways." (PMID 36685857, 2022). "In this study, we further found that IL-6 enhanced PD-L1 expression via modulation of the IL-6-JAK1/Stat3 signaling pathway in cancer cells, which also induced immune evasion." (PMID 35550592, 2022). "Activation of multiple receptor tyrosine kinases can result in sustained feedback activation of STAT3 in cancer drug resistance." (PMID 35197546, 2022). "STAT3 is persistently phosphorylated and activated in many types of human cancer, including hematologic malignancies and solid tumors." (PMID 34953855, 2022). "STAT3 is related to inflammatory effect and apoptosis process, and it is believed to play a key role in cancer progression, angiogenesis, metastasis, and drug resistance." (PMID 35547655, 2022).
cancer (continued). "STAT3, which is closely related to cancer cell invasion and metastasis, was downregulated by EZH2 knockdown." (PMID 35208478, 2022). "Previous work suggested that upregulation of DJ-1 regulates astrogliosis by STAT3 activation and leads to acquiring chemoresistance of cancer cells." (PMID 36202793, 2022). "Still, cancer cells appear to be more responsive to elements that activate STAT3, and once STAT3 is activated, XRCC1 gene and protein levels are elevated and impact the cells ’ responses to DNA damage." (PMID 35457130, 2022). "Excessive activation of the JAK/STAT3 pathway was shown to play an essential role in the development and progression of different cancers." (PMID 35852862, 2022). "Recently, HSP90-mediated activation of STAT3 was shown to activate ubiquitin-proteasome pathway in a FOXO1-dependent manner in cancer cachexia." (PMID 35994202, 2022). "PLKs and signal transducer and activator of transcription 3 (STAT3) exhibit cross-regulatory interactions in human cancers." (PMID 36613455, 2022). "STAT3 activation by osteoclastic CM in IL20RB-expressing cancer cells was also confirmed with a STAT3 luciferase reporter." (PMID 36006737, 2022). "As a result, transcription, agglomeration, and phosphorylation of signaling constituents (such as STAT3) are altered, inducing apoptosis and cell cycle arrest in the G2/M phase of cancer cells." (PMID 36355498, 2022). "Among its most recognized effects is its anticancer potential through inhibition processes of the JAK/STAT3 signaling pathway, whose abnormal activation can direct cascade events involved in the development of cancer." (PMID 36355498, 2022). "MFG-E8 (the downstream factor of TAMs) promoted tumorigenicity and anticancer drug resistance in cancer stem/initiating cells (CSCs) mainly by activating the signal transducer and activator of transcription-3 (STAT3) and sonic hedgehog pathways." (PMID 39280892, 2022). "Our results also showed that LLL12B downregulated the STAT3 downstream gene cyclin D1, which is involved in cancer cell proliferation." (PMID 36009550, 2022). "Choriocarcinoma cell and osteosarcoma cell line and mouse models have shown cancer cell invasiveness is potentially due to LIF-induced STAT3 activation." (PMID 35204717, 2022). "Although STAT3 dysregulation often occurs in many cancer types, the role of STAT3 in large granular lymphocytic (LGL) leukemia is of particular interest." (PMID 35270020, 2022). "Activated STAT3 plays a role in most cancers, mediating the expression of various genes in response to cellular stimulation and playing an important role in cell growth and apoptosis." (PMID 35033067, 2022). "Numerous studies showed that curcumin exerts its antitumor, chemo-preventive, anti-angiogenesis, and anti-cancer activity via hindering STAT3 phosphorylation and blocking related genes in the STAT3-mediated signaling pathway." (PMID 35956419, 2022). "Both STAT3 and NOS2 targets were directly associated with HIF-1 signaling pathway, which played a crucial role in defending the cancer attack." (PMID 35216171, 2022). "Stat3 is hyperactive in a number of human cancers, and the fact that Stat3C, a constitutively active form of Stat3, is sufficient to induce neoplastic transformation of nontransformed mouse fibroblasts points to an etiological role for Stat3 in such tumors." (PMID 36010614, 2022). "Simultaneously, MDSCs play an immunosuppressive role in many cancers, and IL‐10/STAT3 signaling in MDSCs suppresses CD8+ T‐cell proliferation and promotes the development of Tregs in tumors." (PMID 35356799, 2022).
cancer (continued). "Some target genes of NF-κB, like IL-6, are activators of STAT3, which acetylates RelA, retains NF-κB in the nucleus, and thus prolongs its activity in cancer cells." (PMID 35565420, 2022). "Within the STAT family, STAT3 is thought to be involved in hematopoiesis, immunity, and cancer progression." (PMID 35293279, 2022). "Raddeanin A is an attenuator of STAT3 signaling that has been investigated in many cancers as a potential drug for reversal of chemotherapy resistance." (PMID 35204717, 2022). "The signal transducer and activator of transcription 3 (STAT3) is a transcription factor that plays a pivotal role in cancer progression." (PMID 35756080, 2022). "As a tyrosine kinase, JAK activates STAT3 and regulates gene expression, which plays important roles in various types of cancers 9, 10, 19-21." (PMID 35517411, 2022). "Interleukin 6 (IL-6)/Signal Transducer and Activator of Transcription 3 (STAT3) signaling axis has been considered as an essential intrinsic pathway of cancer inflammation." (PMID 35813468, 2022). "In contrast, phosphorylated EZH2 methylates the transcription factor STAT3 at Lys180 (K180), which enhances STAT3-mediated transcriptional activation but also promotes cancer stem cell self-renewal and exerts oncogenic effects." (PMID 36076977, 2022). "STAT3 and P-STAT3 are recognised as oncogenes and are highly expressed in several cancer entities as well as cancer cell lines." (PMID 35303200, 2022). "STAT3 activation has been shown to promote cancer proliferation, growth, and reduces the apoptotic rate." (PMID 35281907, 2022). "Further, the results showed that aging‐ and cancer‐induced muscle atrophy was effectively suppressed by GRd through the suppression of STAT3 phosphorylation and nuclear translocation." (PMID 36127129, 2022). "Further, the interaction between NF‐κB and STAT3 contributes to tumourigenesis in various cancers via induction of molecules that are involved in hypoxia and angiogenesis, and by induction of chemokines and cytokines." (PMID 35194944, 2022). "LncRNA PVT1 promotes cancer initiation and progression by acting as a competing endogenous RNA (ceRNA), activating STAT3 signaling or KAT2A acetyltransferase, or interacting with myelocytomatosis oncogene (MYC)." (PMID 36713226, 2022). "Hispolon induces cell cycle arrest and apoptosis and reduces metastasis by targeting multiple cellular signaling pathways, including the MAPK, PI3K/Akt, and NF-κB pathways, as well as mitochondrial and STAT3 pathways in cancer cells." (PMID 35890318, 2022). "STAT3 also increases the expression of immune checkpoint molecules including PD-L1, which serves to shield the cancer from antigen-specific T cell immunity." (PMID 35406557, 2022). "Since the discovery of the signal transducer and activator of transcription 3 (STAT3) in 1994, the STAT3 pathway has been proven to play a pivotal role in cancer initiation, progression, and metastasis." (PMID 35356799, 2022). "Our study shows that ALT and Brv-A has a potential inhibitory effect over STAT3 activation, FUT4, and P-GP all of which are known to be linked to the drug resistance in cancer." (PMID 35281907, 2022). "The JAK/STAT3 signaling pathway is abnormally activated in cancer cells and plays a key role in cell survival and apoptosis." (PMID 36104717, 2022). "PTPRM can activate STAT3 signaling pathway to enhance the anti-cancer immune responses and rescuing the suppressed immunologic microenvironment in tumors." (PMID 35712349, 2022). "Many inflammatory cytokines have been reported to activate Src kinase and STAT3 signaling in cancers." (PMID 36005200, 2022). "It has long been recognized that IL-6 can activate STAT3 which is closely related to the occurrence, development, and metastasis of malignant tumors during HP infection." (PMID 35958524, 2022).
cancer (continued). "Dual treatment of MSL TNBC cell lines with docetaxel and an IL-6 neutralizing antibody led to a significant reduction in phosphorylation of STAT3, a potent transcription factor for cancer proliferation." (PMID 35260569, 2022). "Many studies have reported that the activation of JAK2/STAT3 pathway contributes to the progression of various cancers." (PMID 35418176, 2022). "Activated STAT3 in cancer cells contributes to oxidative and glycolytic phosphorylation, survival, epithelial-to-mesenchymal transition, proliferation, metastasis, and radiation- and chemotherapy resistance." (PMID 35865518, 2022). "In early CRC, production of both IL-8 and IL-6 by myofibroblasts in the TME is responsible for cancer stem cells expansion and maintenance through the regulation of Notch-STAT3 pathways." (PMID 36289899, 2022). "Inhibiting the STAT-3 pathway at different levels (cytokines, receptors, and kinases) exhibits relative success in cancer." (PMID 35703345, 2022). "This review aims to introduce the history, research advances, and prospects concerning the STAT3 pathway in cancer." (PMID 35356799, 2022). "Collectively, these results indicated that the STAT3 signaling pathway played an important role in the activation of cancer stemness in cancer cells grown on polymer X." (PMID 36359204, 2022). "SMG1 upregulation by IL-6/STAT3 is exacerbated in the context of cancer immunotherapy as there are higher levels of IL-6 hampering the efficacy of the treatment." (PMID 36443756, 2022). "Across a series of cancer cell lines, including MDA-MB-468, CuE (100–200 nM) induced G2/M phase arrest and apoptosis; these cellular outcomes were associated with reduced p-STAT3, p-AKT, and p-ERK with increased levels of p-JNK." (PMID 36355554, 2022). "STAT3 is a critical component of the JAK-STAT signaling pathway; however, deregulated STAT3 signaling results in inflammation, cancer, and fibrosis." (PMID 35052861, 2022). "Through the analysis of signal pathways, this study found that in the ISO–induced apoptosis of AGS cells, the ISO–regulated MAPK signaling pathway and STAT3 signaling pathway, together with the NF–κB signaling pathway, play an anti–cancer role." (PMID 36558992, 2022). "As a member in IL-6 family, leukemia inhibitory factor (LIF) has an crucial role in both embryonic stem (ES) cells and cancer development, which is necessary to maintain mouse ES cells in an undifferentiated condition via STAT3 activation." (PMID 35924148, 2022). "The STAT3 is of importance due to its role in enhancing cancer progression, malignancy, cancer cell migration, and suppression of apoptosis." (PMID 35566382, 2022). "Stat3 activation induces many protumor molecules related to cancer cell growth, stem cell properties, immunosuppression, and angiogenesis." (PMID 35132816, 2022). "STAT3 was not previously identified as a regulator of XRCC1, but the data here demonstrate that STAT3 activation promotes resilience to DNA damage, which likely contributes to chemoresistance or even radiotherapy resistance in cancer cells." (PMID 35457130, 2022). "Over-active p-STAT3 helps cancer cells evade the immune system through the upregulation of PD-L1 expression." (PMID 35158821, 2022). "Phosphorylated Stat3 (pStat3) was expressed at lower frequency in carcinoma epithelial cells compared to cells from the other stages and more frequently in MT glands." (PMID 35505346, 2022). "The binding of S1P to S1PR1 resulted in persistent signal transducer and activator of transcription 3 (STAT3) activation promoting cancer cell progression." (PMID 33920887, 2021). "JAK2/STAT3 inhibition can dampen the polarization of M2-type macrophages and slow down the progression of cancer." (PMID 34604066, 2021). "In conclusion, these results suggest that Alp alleviates cancer cachexia progression and prevents muscle atrophy via activating PPARγ and thereby inhibiting phosphorylation of NF-κB and STAT3." (PMID 34093209, 2021).